BMAL1 (basic helix-loop-helix ARNT like 1)
Diseases named in the same sentence as BMAL1 in open-access papers (continued):
Sharing a sentence is not in itself a finding about the gene and the disease.
Hepatic steatosis (12 papers, 2013 to 2025). Steatosis is a term used to denote lipid accumulation within hepatocytes. "During high-fat feeding, hepatic Bmal1 deficiency results in marked insulin resistance and liver steatosis." (PMID 39060446, 2024). "Global and tissue specific knock-out or mutation of clock genes (Rev-erbα/β-/-, Cry1/2-/-, Bmal1-/- and ClockΔ19, Bmal1Δhep) promote hepatic steatosis, and alter blood glucose and lipid homeostasis in lean and high fat diet (HFD) fed obese mice." (PMID 32699233, 2020). "PPARGC1α has been shown to induce expression of Clock, Bmal1, Rev-erbα, and Rev-erbβ and increase transcriptional activity of RORα, with deficiency of this protein contributing to hepatic steatosis after short-term starvation." (PMID 23951220, 2013). "CLOCK:BMAL1 are pioneering transcription factors for rhythmic genes, and their disfunction (i.e., through genetic or pharmacologic interventions) has been associated with metabolic disorders, including fatty liver disease." (PMID 39060446, 2024). "In NDI1-expressing adipocyte-Bmal1-KO mice, we also observed reduced hepatic steatosis and smaller white adipocyte size." (PMID 41279878, 2025). "For example, Clock mutant and Bmal1–/– mice present hyperlipidemia and hepatic steatosis, while Per2–/– mice show altered lipid metabolism." (PMID 34298842, 2021). "Liver-specific knockout or depletion of Bmal1 in ethanol-fed mice leads to more severe hepatic steatosis and damage." (PMID 33381029, 2020). "Our data show that Physcion eliminates SREBP1 in acute ethanol-induced hepatic steatosis by modulating Bmal1 and AMPK." (PMID 33381029, 2020). "Indeed, liver specific ablation of Bmal1 or Rev-Erbα/β show increased hepatic steatosis and dyslipidemia after HFD feeding." (PMID 34298842, 2021). "Moreover, research utilizing liver-specific Bmal1 knockout mice subjected to ethanol-fed conditions revealed a concomitant inhibition of both de novo lipogenesis and fatty acid oxidation pathways, culminating in hepatic steatosis." (PMID 39062955, 2024). "BMAL1 ablation inhibits the expression of CD36 and PPARγ signaling and attenuates hepatic steatosis." (PMID 40083324, 2025). "Previous literature reported that BMAL1 deletion inhibits the expression of CD36 and peroxisome proliferator-activated receptor γ (PPARγ) and attenuates hepatic steatosis." (PMID 40083324, 2025). "Thus, neutrophil depletion decreases Bmal1 expression and the circadian locomotor output cycles kaput (CLOCK) and reduces overall JNK activation, decreasing hepatic steatosis." (PMID 38979415, 2024).
sleep disorder (12 papers, 2020 to 2025). A change from the patient's baseline sleeping pattern, in the hours slept and/or an alteration/dysfunction in the stages of sleep. "Abnormal expression levels of Per2, Clock, and Bmal1 in oral mucosa and mononuclear cells at certain time points were detected in patients with sleep disorders after TBI." (PMID 38285094, 2024). "Understanding the role of Bmal1 in the corneal endothelium may help us to better define the pathogenesis and development of ocular diseases induced by sleep disorders." (PMID 38907352, 2024). "We found that the expression of Per2, Clock, and Bmal1 in oral mucosal cells and peripheral blood monocytes in patients with sleep disorders after craniocerebral injury was significantly lower than that in patients with normal sleep after craniocerebral injury." (PMID 36303945, 2022). "Moreover, microglial Bmal1 has been proven to be an important molecular player in the inflammatory response and in different pathological processes, such as neurological diseases and sleep disorders." (PMID 35845604, 2022). "Likewise, the deletion of mouse astrocytic Bmal1 leads to the impairment of cognitive functions, majorly affecting the declarative memory, as well as to an imbalance of the GABAergic system, resulting in the development of neurological and sleep disorders." (PMID 35845604, 2022). "Sleep disorders disrupt the expression of circadian rhythm-related genes (such as CLOCK and BMAL1) via epigenetic mechanisms, further worsening neuronal damage." (PMID 40264463, 2025). "Then, the expression of Nox4, Clock, and Bmal1 were detected to identify how circItm2b exerted its function in TBI and in subsequent sleep disorders after TBI." (PMID 39962534, 2025). "In clinical studies, alterations in clock genes (particularly BMAL1) have been frequently identified in children with ADHD, who often have comorbid sleep disorders." (PMID 40137518, 2025). "Circadian rhythm genes mainly altered in malignant nodules, and sleep disorders may be involved in the occurrence of elderly thyroid malignancy through the high expressions of CLOCK and BMAL1, and low expression of CRY2." (PMID 34211057, 2021).
Hypoglycemia (11 papers, 2004 to 2024). A decreased concentration of glucose in the blood. "In particular, liver-specific disruption of Bmal1 in mice results in hypoglycemia, higher glucose clearance and loss of rhythmic expression of clock-regulated metabolic genes, highlighting the importance of the peripheral oscillators in modulating circadian physiology." (PMID 21731503, 2011). "Liver Bmal1-knockout led to hypoglycemia in the fasting phase and induced an abnormal increase in glucose clearance ability." (PMID 31851682, 2019). "Gluconeogenesis is abolished by deletion of Bmal1 and is depressed in Clock mutants, but the counterregulatory response of corticosterone and glucagon to insulin-induced hypoglycaemia is retained." (PMID 15523558, 2004). "Our studies revealed a profound role for core clock genes—Bmal1 and Clock—in regulating recovery from insulin-induced hypoglycaemia." (PMID 15523558, 2004). "Furthermore, Bmal1−/− knock-out mice showed disruption in the expression of genes related to glucose regulation, resulting in inability of the liver to extract glucose at the required time intervals, which led to hypoglycemia during fasting hours." (PMID 39519533, 2024). "For instance, whole-body inactivation of brain and muscle ARNT-like 1 (Bmal1) or circadian locomotor output cycles kaput (Clock) could suppress glucose rhythm, impair gluconeogenesis, and inhibit glucose recovery in insulin-induced hypoglycemia." (PMID 31851682, 2019). "Deletion of BMAL1 in hepatocytes did not alter baseline glucose levels, the hypoglycaemia in NF mice challenged with LPS at ZT12 and DF mice at ZT0, or glycogen stores in the fed vs. fasted state." (PMID 33980856, 2021). "Mice lacking hepatic BMAL1 presented hypoglycemia during the day, due to an exacerbated glucose clearance, and disruption of circadian expression of glucose regulatory genes in the liver." (PMID 34298842, 2021). "Finally, BMAL1 control glycaemia by regulating GLUT2 expression; in turn, hepatic deletion of Bmal1 induces fasting hypoglycemia, decreased liver glycogen and increased glucose clearance." (PMID 34298842, 2021). "Here the liver-specific inactivation of Bmal1 resulted in severe hypoglycaemia during their inactivity period, but not if Bmal1 was inactivated in all the other cell types excluding the liver; comparable results were obtained after inactivation of Per1/2." (PMID 25665169, 2015). "Whole-body BMAL1 knockout mice presented with diminished gluconeogenesis and could not recover from insulin-induced hypoglycemia." (PMID 28352282, 2017). "BMAL1 and CLOCK are also major factors in the regulation of glucose and triglyceride homeostasis, as gluconeogenesis was abolished by deletion of Bmal1 and depressed in Clock mutants, even if the response of glucagon and corticosterone to insulin-induced hypoglycaemia was retained." (PMID 25665169, 2015).
liver cancer (11 papers, 2018 to 2025). An epithelial or non-epithelial malignant neoplasm that arises from the liver. "In liver cancer cells, Bmal1 or Clock down-regulation induced apoptosis and arrested the cell cycle at the G2/M phase." (PMID 37504857, 2023). "Interestingly, induced expression of BMAL1 in HNF4α-positive liver cancer cells impairs growth in culture and in vivo." (PMID 37600688, 2023). "P2-HNF4α, which is often upregulated in liver cancer, is selectively induced in HCC, where it directly inhibits the expression of BMAL1 and leads to the cytoplasmic expression of the P1 isoform." (PMID 37600688, 2023). "Our findings establish anti-apoptotic roles of the master clock regulators BMAL1 and CLOCK in promoting proliferation of liver cancer cells and reveal an underpinning mechanism being mediated by the cancer-state essential gene Wee1." (PMID 36595671, 2023). "BMAL1 and HNF4A ChIP-seq signals from human liver cancer Hep3B or HepG2 cells were plotted correspondingly at each position of the BMAL1 binding sites we just profiled in U2OS-GFP and U2OS-HNF4A2 cells." (PMID 34732735, 2021). "Importantly, forced expression of BMAL1 in HNF4α-positive liver cancer cells impairs spheroid growth in culture and tumor growth in vivo, demonstrating that manipulation of the circadian clock in HNF4α-positive HCC could be a realistic strategy to slow or reverse growth of human HCC." (PMID 30341289, 2018). "We previously showed in models of MYC amplification representing liver cancer (tumors and cell lines) and Burkitt’s Lymphoma that suppressing amplified MYC leads to changes in clock gene expression, including increasing BMAL1 (which suggested that MYC suppressed BMAL1 in these settings)." (PMID 37639465, 2023).
mood disorder (11 papers, 2013 to 2025). A cognitive disorder a disturbance in which the person's mood is hypothesized to be the main underlying feature. "In fact, mood disorders have been linked with alterations in the expression of circadian rhythm genes such as Clock, Bmal1, and Per." (PMID 40746483, 2025). "Models with genetic BMAL1 disruption have elucidated the BMAL1-dependent mechanisms associated with the development of mood disorders." (PMID 41440117, 2025). "Variants in genes including PER3, CLOCK, and BMAL1 influence not only circadian phase preference but also cognitive performance patterns, mood disorder susceptibility, and drug metabolism." (PMID 41226802, 2025). "This indicates that BMAL1 deficiency also affects neurotransmitter systems in the pathogenesis of mood disorder." (PMID 41440117, 2025). "Furthermore, mood disorders have been associated with changes in the expression of circadian rhythm genes such as Clock, Bmal1, and Per." (PMID 39584972, 2024). "This review summarizes data on BMAL1 functions in different cell types of the mammalian nervous system and its implications for brain pathologies, including trauma, neurodegeneration, and mood disorders." (PMID 41440117, 2025). "In this review, we have collected data from human and animal studies concerning the roles of BMAL1 in processes such as neuroinflammation, trauma and neurodegeneration, neurodevelopment and myelinization, mood disorders, addictions, cognitive functions, and neurosignaling." (PMID 41440117, 2025). "Studies on the effects of BMAL1 ablation in a monkey model, together with appropriate behavioral assays, could help us to understand the molecular basis of the circadian link to mood disorders." (PMID 34691834, 2019). "However, since no change in circadian period was observed in Bmal1-cKO mice, our results highlight a major causal role of circadian genes in mood disorders independent of their effects on circadian rhythm regulation." (PMID 40646562, 2025).
steatosis (11 papers, 2018 to 2026). Increased lipid within the cytoplasm of cells. "Exogenous melatonin has a protective effect: it reduces necrosis and steatosis, partially restores circadian genes (Per2 and BMAL1), and normalizes biochemical parameters (ALT, AST, and glucose)." (PMID 41614811, 2025). "Autophagy activity was inhibited and steatosis was deteriorated after EtOH-treated L-02 cells were cotransfected with Rev-erbα shRNA and Bmal1 siRNA." (PMID 34246287, 2021). "Bmal1 is thought to induce lipogenesis, whereas Nr1d2 controls lipid metabolism and its reduced expression promotes lipogenesis and steatosis." (PMID 33287957, 2020). "In both models, the reduction of neutrophil infiltration correlated with decreased levels of liver Bmal1 expression and protection from jet lag-induced steatosis." (PMID 33287957, 2020). "Jet lag-induced steatosis was less severe in neutropenic mice, and disruption of diurnal liver expression of Bmal1 detected in control jet-lagged mice was partially ablated in neutropenic mice." (PMID 33287957, 2020). "In contrast, hepatic PPARα, PPARβ/δ, Foxa2, and circadian clock BMAL1 exert anti-steatosis action by promoting fatty acid β oxidation." (PMID 30013137, 2018). "Steatosis significantly blunted the circadian pattern of clock genes such as Bmal1, Clock, and Per in cultured hepatocytes and liver." (PMID 30322022, 2018). "On the other hand, from the different compounds present in the GSPE extract, we provide evidence for the strong role of (+)‐catechin, which was able to rescue—in a dose‐dependent manner—the dampened Bmal1‐luc rhythms in an in vitro steatosis model of murine hepatocytes." (PMID 39523911, 2024). "This BMAL1-dependent lipogenic axis is needed to protect against alcoholic fatty liver disease, and mice with liver-specific Bmal1 deletions present increased steatosis and injured liver after an ethanol-enriched diet, showing a suppression of de novo lipogenesis and fatty acid oxidation." (PMID 34298842, 2021). "Interestingly, mice with neutropenia, defective neutrophil infiltration or lacking elastase were protected against steatosis correlating with lower JNK activation, reduced Bmal1 and increased FGF21 expression, together with decreased lipogenesis in the liver." (PMID 33287957, 2020).
viral infection (11 papers, 2012 to 2025). "On the other hand, BMAL1 is recognized to play a crucial role in regulating pulmonary inflammation and enhancing susceptibility to viral infection." (PMID 36366382, 2022). "In various bacterial and viral infection models, the loss of the circadian gene BMAL1 resulted in increased viral burden and disease severity." (PMID 36366382, 2022). "BMAL1 is a key component of the circadian clock; mice deficient in BMAL1 show impaired circadian behaviour and many physiological abnormalities including glucose homeostasis, insulin production, accelerated aging and increased susceptibility to virus infections." (PMID 28963570, 2017). "Silencing the BMAL1 gene indicates that the proper functioning of the molecular circadian mechanism is essential for the immune response to viral infections." (PMID 40284797, 2025). "The CLOCK/BMAL1 complex regulates the expression of pattern recognition receptors (PRRs) involved in nucleic acid sensing during viral infections, an essential function of the innate immune system." (PMID 40284797, 2025). "The seasonal variation of BMAL1 expression, reaching its lowest values in winter, seems to contribute to the high occurrence of respiratory viral diseases in this season since low BMAL1 expression enhances viral disease." (PMID 32012758, 2020). "The Bmal1 knockout findings suggest that proper functioning of the molecular clockwork is necessary for the immune response towards viral infections and the subsequent disease." (PMID 32012758, 2020). "Influenza A virus infection in BMAL1 KO mice further enhance the severity of virus infection resulting in increased morbidity and mortality." (PMID 25923474, 2015). "Interestingly, a recent report indicates that CLOCK and BMAL1 play a role in transcriptional activation after viral infection." (PMID 22900038, 2012). "CLOCK, BMAL1, and REV-ERB regulate the expression of the pattern recognition receptors (PRRs) that recognize viral nucleic acids during viral infections, and cells lacking Bmal-1 are more vulnerable to infection by RNA virus infection." (PMID 37999239, 2023). "In mice lacking BMAL1, the levels of virus replication were independent of the time of day at which the viral infection was performed." (PMID 32012758, 2020). "Therefore, we selected BMAL1 and CRY1 for qRT-PCR validation and found that the expression of BMAL1 and CRY1 was significantly downregulated after SVA infection, indicating that after viral infection, piRNAs may exert an effect on circadian rhythm." (PMID 37323834, 2023).
Arrhythmia (10 papers, 2015 to 2024). Any cardiac rhythm other than the normal sinus rhythm. "Whole-body deletion of Bmal1 in mice causes behavioral arrhythmias, accompanied by many adverse effects related to early aging." (PMID 37299510, 2023). "More invasive studies are needed to determine whether the loss of the Bmal1 in mice with the ΔKPQ-Scn5a mutation have higher susceptibility to arrhythmias and/or ventricular tachyarrhythmias." (PMID 34248669, 2021). "In this study, we evaluated the absence of the Bmal1 gene in mice as a proper model of daily arrhythmia and how this internal dysregulation manifests in terms of activity and motivation for natural rewards." (PMID 39045857, 2024). "It has been observed that the Bmal1 gene significantly determined circadian rhythms since Bmal1 knockout mice exhibited a severe phenotype with arrhythmia (no rhythmic activity), inhibiting circadian rhythms." (PMID 35293154, 2022). "Bmal1 expression was reduced by 65% in heterozygous Syt10-Cre mice (Syt10-Cre+/−; Bmal1loxp/loxp), which did not result in circadian arrhythmia, whereas Bmal1 transcript levels decreased by 83% in homozygous Syt10-Cre mice (Syt10-Cre+/+; Bmal1loxp/loxp) that was accompanied by arrhythmia." (PMID 36593479, 2023). "Consequently, our experimental findings demonstrated that although injecting cells with Bmal1 shRNA did not result in critical arrhythmia, it diminished the circadian rhythm system." (PMID 35293154, 2022). "Moreover, even though Bmal1 shRNA injection with the NTW array did not cause complete arrhythmia (lacking steady rhythms) in the SCN slice, effects on Per1::luc emission rhythms are proposed to depend on the identity and percentage of pacemaker cells injected with Bmal1 shRNA." (PMID 35293154, 2022).